PTX3 (pentraxin 3)
Diseases named in the same sentence as PTX3 in open-access papers (continued):
Sharing a sentence is not in itself a finding about the gene and the disease.
periodontitis (continued). "In a rat model of periodontitis, high levels of the PTX3 protein were found in the gingival tissue and serum, which correlated with alveolar bone resorption and inflammatory cells' infiltration." (PMID 31787987, 2019). "Among other acute phase proteins, PTX3 levels were elevated in the gingival crevicular fluid and plasma of patients with periodontitis, and correlated with the clinical score of the disease." (PMID 31787987, 2019). "Levels of PTX3 in gingival tissue were significantly higher in experimental periodontitis group after 10 days." (PMID 22966213, 2012). "In the present study, PTX3 levels were investigated in gingival tissue and serum of rats with experimental periodontitis." (PMID 22966213, 2012). "Very recent clinical data suggested that gingival crevicular fluid PTX3 level is higher in periodontally diseased sites as compared to healthy sites in the same patient with chronic periodontitis." (PMID 22966213, 2012). "The results of the present study clearly show that the concentration of PTX3 in gingival tissue and serum was positively correlated with alveolar bone resorption and with inflammatory cells in epithelium both in experimental periodontitis groups." (PMID 22966213, 2012). "This is consistent with the results of the present study that levels of PTX3 in gingival tissue was significantly higher in experimental periodontitis group after 10 days." (PMID 22966213, 2012). "Similarly, a randomized controlled clinical research indicated that local application of TTO gel (5 ml TTO was mixed into methylcellulose gel) reduced pocket probing depth index and PTX3 level in subjects with periodontitis." (PMID 38952769, 2024). "Therefore, to consider Pentraxin-3 as an inflammatory biomarker of periodontitis in GCF, further studies withlarger sample sizes and more extended follow-up periods in different populations are required." (PMID 36506882, 2022). "Furthermore, PTX3 is highly expressed in periodontitis; after experimental induction of periodontitis, serum PTX3 levels were significantly increased 24 h after injection and continued to increase for 21 days." (PMID 34211440, 2021). "Indeed, PTX3 concentration in the gingival tissue of patients with generalized aggressive periodontitis was higher than in those with chronic periodontitis." (PMID 31787987, 2019). "In addition to periodontitis, PTX3 (and other inflammatory mediators) was found abundant in the periodontal ligament of the tension zone during orthodontic tooth movement, characterized by enhanced osteoclast activity and rapid bone remodeling." (PMID 31787987, 2019). "However, these inflammatory mediators have been mostly studied in the context of pathological inflammation (i.e., arthritis, periodontitis, osteomyelitis), whereas our study determined the role of PTX3 in physiological bone remodeling and repair." (PMID 29556234, 2018). "The hypothesis tested is that synthesis of gingival tissue and serum PTX3 increases in the experimental periodontitis model (with 10 days and 40 days periods)." (PMID 22966213, 2012). "The hypothesis, synthesis of gingival tissue and serum PTX-3 increases in the experimental periodontitis model (with 10-day and 40-day periods), was tested by detecting gingival tissue and serum PTX-3 levels in rats with experimental periodontitis." (PMID 22966213, 2012). "The present study was undertaken to test the hypothesis that synthesis of gingival tissue and serum PTX-3 increases in the experimental periodontitis model (with 10 days and 40 days periods) in rats which can easily be standardized." (PMID 22966213, 2012). "A higher concentration of pentraxin-3 in GCF of CP patients than in healthy controls may highlight the role of this marker in the pathogenesis of periodontitis.Therefore, it can be used as an inflammatory marker in periodontal disease and can be employed to detect individuals at risk for CP." (PMID 36506882, 2022).
periodontitis (continued). "Thus, the quantitative assessment of PTX3 by ELISA methods could be used as an adjuvant-testing tool for periodontitis." (PMID 34830557, 2021). "Therefore, we aimed to test the hypothesis that LPS-induced periodontitis could contribute to peripheral changes of inflammatory biomarkers (IL-6, IL-10, PTX3, and sTWEAK) in rats." (PMID 31583485, 2020). "Moreover, recent studies indicated that periodontitis may lead to systemic upregulation of both inflammatory and endothelial dysfunction markers, including PTX3, serum amyloid A (SAA), and amyloid-β peptide." (PMID 31787987, 2019). "Also, given the prominent protective role of PTX3 in the resistance to selected microbial pathogens, assessing its function in bone infections other than periodontitis (e.g., osteomyelitis) is relevant and deserves further investigations, owing to its potential application in human diseases." (PMID 31787987, 2019). "SerumTNF-related weak inducer of apoptosis (s-TWEAK) and pentraxin-3 (PTX3), which are vascular systemic inflammatory mediators have also been suggested to be higher in periodontitis patients who are chronic migraineurs." (PMID 38699683, 2024). "Our study showed that both groups of periodontitis patients (P and P + O) expressed significantly higher levels for SAA and PTX3." (PMID 37240630, 2023). "They reported not only a significant increase in the concentration of pentraxin-3 in the plasma and GCF of patients with gingivitis compared to healthy controls but also in patients with periodontitis compared to those with gingivitis." (PMID 36506882, 2022). "NSPT produced a significant improvement of the clinical periodontal status of periodontitis patients with chronic hepatitis C, as reflected by the clinical periodontal examination and ELISA assessment of the GCF PTX3 and CRP levels." (PMID 34830557, 2021). "Local ozone therapy inhibits the expression of inflammatory factors such as pentraxin-3 (PTX-3), IL-1β, and high-sensitivity C-reactive protein (Hs-CRP) in periodontitis patients." (PMID 32398953, 2020). "This study aimed to assess the effect of non-surgical periodontal therapy on GCF level of pentraxin-3 in patients with chronic periodontitis." (PMID 36506882, 2022). "Most assessed parameters (clinical and immunological) showed a similar evolution in the groups of patients with periodontitis (HCV+P and P), from baseline to recall, apart from the GCF PTX3 parameter, which expressed a more important decrease in P group (−43.75%), than in the HCV+P one (−39.47%)." (PMID 34830557, 2021). "Although the serum cytokine and APR levels were not statistically significant between study groups, the positive correlations between the PISA values and SAA and PTX3 in CAD (-) groups with/ without periodontitis deserve further attention." (PMID 29742255, 2018). "However, when the strengths of this study were considered, it can be suggested that our study has driven some APR (PTX3 and SAA) forward in the relationship between CAD and periodontitis." (PMID 29742255, 2018). "The present study results clearly showed that PTX3 levels in gingival tissue were significantly higher in experimental periodontitis after 10 days but were not different from control at 40 days." (PMID 22966213, 2012). "Although the difference in the serum levels of PTX3 was not significant, there was a proportionate increase in serum levels from healthy controls to experimental periodontitis groups after 40 days to after 10 days." (PMID 22966213, 2012). "As highlighted by the ELISA analysis of the PTX3 and CRP markers in gingival fluid samples, it could be said that non-surgical periodontal therapy has a relevant, improving, impact on the local homeostasis of periodontitis + hepatitis C patients." (PMID 34830557, 2021). "This may suggest that GCF PTX3 levels are independent of systemic illness concerning periodontitis patients." (PMID 34830557, 2021).
periodontitis (continued). "Among the detected inflammatory mediators in saliva samples, TWEAK/TNFSF12, IL-35, IFN-α2, pentraxin-3, gp130/sIL6Rb, sIL-6Ra, IL-19 and sTNF-R1 were found to be significantly increased in patients with periodontitis and RA compared to non-RA group with periodontitis." (PMID 35360114, 2022). "Our data showed that several inflammatory mediators were increased in RA-periodontitis saliva as compared to non-RA, including TWEAK/TNFSF12, pentraxin-3, IL-19, IL-35, gp130/sIL6Rb, sIL-6Ra, IFN-α2 and sTNF-R1." (PMID 35360114, 2022). "Since there is paucity of research on the effects of non-surgical periodontal therapy (scaling and root planing) on GCF level of pentraxin-3, this study aimed to assess the effect of non-surgical periodontal therapy on GCF level of pentraxin-3 in patients with chronic periodontitis." (PMID 36506882, 2022).
asthma (19 papers, 2012 to 2026). "PTX3 concentrations in serum can fluctuate during asthma, reflecting the inflammatory processes associated with this respiratory condition." (PMID 38275403, 2024). "The activation of PTX3 has been observed in many inflammation-associated diseases, including asthma." (PMID 36530573, 2022). "Recently, it has been reported that PTX3 deficiency enhances interleukin (IL)-17A–dominant pulmonary inflammation in an ovalbumin (OVA)-induced mouse asthma model." (PMID 32938460, 2020). "However, another independent study found that Ptx3 deficiency in an OVA-induced mouse asthma model resulted in augmented AHR, mucus production, and IL-17-dominant airway inflammation." (PMID 37957139, 2023). "In younger populations, elevated levels of PTX-3 have been associated with neonatal sepsis, severe pediatric microbial infections, and autoimmune diseases, such as childhood-onset systemic lupus erythematosus, juvenile idiopathic arthritis, and asthma." (PMID 32670996, 2020). "Recent reports, all using ovalbumin have shown aggravation of asthma by pentraxin 3, prostaglandin E2, IL-15-deficiency or suppression of asthma by anti-inflammatory protein 2 from hookworms [20▪▪], natural killer (NK) receptor 1 and inhibition of hypoxia inducible factor-1α." (PMID 28346234, 2017). "Pentraxin 3 expression is also found to be associated with the pathology of asthma." (PMID 23755050, 2013). "PTX3 concentrations in sputum have been studied in both pediatric and adult populations with asthma, where it was found to be elevated compared with levels in healthy controls." (PMID 38275403, 2024). "In the context of asthma, PTX3 regulates airway inflammation, airway remodeling, and oxidative stress, making it a potential biomarker for asthma severity and a therapeutic target." (PMID 38275403, 2024). "Xie’s study reported that administration of PTX3 provoked airway inflammation in asthma by promoting both eosinophils and neutrophils lung infiltration." (PMID 39666228, 2024). "Mechanistically, m6A-sequencing shows that loss of METTL3 impairs the m6A-YTHDF3-dependent degradation of PTX3 mRNA, while higher PTX3 expression positively correlates with asthma severity through promoting M2 macrophage activation." (PMID 37957139, 2023). "PTX3 significantly enhances inflammatory cell infiltration in lung tissue, mucus production and collagen deposition in asthma mouse models." (PMID 36336784, 2022). "Pentraxin-3 levels were also considerably higher in bronchoalveolar lavage fluid (BALF) of patients with severe asthma." (PMID 35387000, 2021). "ii) the ability of GCs to increase the expression of pentraxin-3 in ASM cells is defective in patients with severe asthma." (PMID 35387000, 2021). "Th17 response is usually associated with increased neutrophilic inflammation (as seen in pentraxin-3-/- mice) and, thus, more severe asthma." (PMID 35387000, 2021). "Further study is still needed to provide a comprehensive understanding of the exact mechanism by which PTX3 regulates airway inflammation in asthma." (PMID 32938460, 2020). "Our group previously reported differential expression of pentraxins including PTX3 in asthmatic patients, which partly reflected heterogeneity of innate immunity in asthma." (PMID 32938460, 2020). "In a mice study of asthma, exogenous pentraxin 3 promoted both eosinophilic and neutrophilic airway inflammation." (PMID 33233354, 2020). "The goal of this study was to further investigate the effect of recombinant PTX3 administration on the phenotype of asthma." (PMID 32938460, 2020). "Sputum PTX3 levels were also shown to be increased in children with asthma and reported to be a candidate biomarker for evaluation of airway inflammation and remodeling." (PMID 32938460, 2020). "In concert with this suggestion, we recently demonstrated that PTX3 deficiency resulted in excessive inflammation, AHR, and airway remodeling using OVA model of asthma." (PMID 31437159, 2019).
asthma (continued). "Previously, we showed that PTX3 expression is increased in bronchial biopsies and bronchoalveolar lavage fluid of subjects with severe asthma when compared to healthy donors." (PMID 31437159, 2019). "Studies examining the role of potential proteolytic cleavage of PTX3 would provide detailed insight into the regulation of PTX3 expression in asthma." (PMID 23755050, 2013). "Bronchial biopsy specimens from healthy controls (n = 10) and subjects with allergic asthma (n = 27; 9 with mild, 10 with moderate, and 8 with severe asthma) were used for immunohistochemistry staining using mAb anti-human PTX3." (PMID 22529962, 2012). "As an immune modulator, PTX3 may be influenced by altered immune responses in asthma, with decreased concentrations potentially indicating a shift in the immune profile in favor of other immune molecules or pathways." (PMID 38275403, 2024). "m6A-seq and MeRIP-qPCR findings indicate that m6A /METTL3/YTHDF3 interactions are involved in the repression of M2 macrophage activation by accelerating the degradation of Pentraxin 3 (PTX3) transcripts, which is widely regarded as a regulator of inflammation and asthma." (PMID 37957139, 2023). "Importantly, STX17, as a key target of PTX3-mediated macrophage homeostasis, was also more abundant in monocyte-derived macrophages isolated from asthma patients." (PMID 37957139, 2023). "We were the first to examine the role and function of pentraxin-3 in patients with asthma." (PMID 35387000, 2021). "We and others extensively examined the specific role of pentraxin-3 in asthma." (PMID 35387000, 2021). "In another study, sputum pentraxin-3 concentration was significantly higher in children with asthma than in control subjects and correlated with atopic status and disease severity among patients with asthma." (PMID 35387000, 2021). "This suggests that pentraxin-3 may help prevent neutrophilic inflammation seen in patients with severe asthma." (PMID 35387000, 2021). "Indeed, pentraxin-3 deletion promotes more severe forms of asthma characterized mainly by a steroid-resistant Th17 dominant phenotype." (PMID 35387000, 2021). "In summary, serum PTX3 levels might be a valuable marker to demonstrate the presence of low‐grade inflammation in asthma." (PMID 32246830, 2020). "We evaluated effect of recombinant PTX3 on asthma phenotype through both asthma models." (PMID 32938460, 2020). "Recently, PTX3 deficiency was shown to result in augmented airway hyperresponsiveness (AHR), mucus production, and IL-17-dominant pulmonary inflammation in an OVA-induced mouse asthma model." (PMID 32938460, 2020). "Accordingly, both eosinophilic and neutrophilic asthma models were applied to comprehensively evaluate the effect of exogenous PTX3 on the phenotype of asthma, by assessing AHR, inflammatory cell infiltration, cytokine production, mucus production and collagen disposition." (PMID 32938460, 2020). "Taken together, these data demonstrate that PTX3 has the ability to inhibit FGF2-induced migration of HASMC at least in vitro suggesting its role as potential protective mechanism against remodelling observed in asthma." (PMID 22529962, 2012). "However, serum PTX3 levels seem to be inadequate as marker for asthma management, and it remains a matter of debate whether PTX3 might be directly involved in the etiology of allergic airway inflammation." (PMID 32246830, 2020). "Thus, our study didn’t support PTX3 administration as a treatment option for asthma." (PMID 32938460, 2020). "In view of the complexity role of PTX3 in disease pathogenesis it was necessary to identify whether PTX3 treatment would provide protection against unbalanced inflammatory responses in asthma, and elucidate the exact role of PTX3 in the disease pathogenesis." (PMID 32938460, 2020). "We investigated circulating PTX3 and TRX1 levels to predict oxidative stress in asthmatic patients’ serum and investigate them as a potential biomarker in asthma." (PMID 38275403, 2024).
asthma (continued). "We previously showed that PTX3 inhibits FGF2 induced cell migration, an important factor contributing to increase smooth muscle mass in asthma." (PMID 26644796, 2015). "Since TNF is one of the critical proinflammatory effector cytokines in asthma, and has been shown to induce multiple inflammatory genes in HASMC, we further characterized the kinetic of TNF induced PTX3 mRNA expression using quantitative real-time RT-PCR." (PMID 26644796, 2015). "PTX3 and TRX1 have been identified as potential markers of oxidative stress in asthma." (PMID 38275403, 2024). "Since TNF induces pentraxin-3 secretion and the later promotes the secretion of eotaxin-1/CCL11, it is legitimate to speculate that pentraxin-3, in an autocrine manner, mediates some of the effects of TNF in asthma." (PMID 35387000, 2021). "When ASM cells were treated with a variety of cytokines found in high levels in the airways of asthma such as TNFα, IL-1β, Th1 (IFN-γ), Th2 (IL-4, IL-9, and IL-13), and Th17 (IL-17) cytokines, only TNF and IL-1β were able to increase pentraxin-3 secretion significantly." (PMID 35387000, 2021). "iii) different pentraxin-3 isoforms are expressed in patients with severe asthma to explain why the high levels of pentraxin-3 seen in these patients are not protective in deterring the inflammatory response." (PMID 35387000, 2021). "Plasma concentrations were not different in the two asthma subgroups, whereas sputum pentraxin-3 levels were higher in non-eosinophilic asthma." (PMID 35387000, 2021). "Our study suggests a novel mechanism involving PTX3 by which HASMC may regulate airway inflammation and immune response in asthma." (PMID 31437159, 2019). "It is also tempting to speculate that PTX3 released from HASMC upon GCs stimulation prevents the excess of inflammatory cells recruitment and airway remodeling, hence identifying a new mechanism by which GC mitigate airway inflammation in asthma." (PMID 31437159, 2019). "Hence, it is plausible that PTX3-mediated eotaxin-1/CCL11 release may down-regulate exaggerated neutrophilic inflammation, via the suppression of CXC chemokine, especially in the context of severe asthma." (PMID 31437159, 2019). "In agreement with the role of PTX3 in matrix organization, our IHC staining showed a significant PTX3 staining within the ASM bundles of asthmatic bronchial tissue compared to healthy donors, which may provide another possible explanation of airway remodeling observed in asthma." (PMID 22529962, 2012).